NSD1 (nuclear receptor binding SET domain protein 1)
Diseases named in the same sentence as NSD1 in open-access papers (continued):
Sharing a sentence is not in itself a finding about the gene and the disease.
metastatic melanoma (2 papers, 2012 to 2022). A melanoma that has spread from its primary site to another anatomic site. "Indeed, enhanced NSD1 mRNA level was observed in cutaneous metastatic melanoma cells compared to skin melanocytes, suggesting that NSD1 is pro-tumoral." (PMID 36230787, 2022). "By contrast, a down-regulation of NSD1 expression was observed during the progression from nonmetastatic to metastatic melanoma." (PMID 36230787, 2022). "Therefore, the expression pattern of human NDRG2, VDR, NSD1, CTCF and SRC genes in several human metastatic melanoma cell lines in comparison to primary melanocytes were analyzed at mRNA level by RT-qPCR methodology." (PMID 22984562, 2012).
osteoarthritis (2 papers, 2024 to 2025). A noninflammatory degenerative joint disease occurring chiefly in older persons, characterized by degeneration of the articular cartilage, hypertrophy of bone at the margins and changes in the synovial membrane. "Ferroptosis could promote osteoarthritis progression, but whether NSD1 influences KOA ferroptosis remains unknown." (PMID 40584820, 2025).
pancreatic cancer (2 papers, 2022 to 2023). "Notably, when compared with NSD1 and NSD2, we find that NSD3 is prominently expressed, and its expression is significantly linked with clinical outcome in pancreatic cancer." (PMID 37062069, 2023).
sarcoma (2 papers, 2020 to 2022). A usually aggressive malignant neoplasm of the soft tissue or bone. "For instance, sarcomas harbor high-frequency H3.3G34R and H3.3K36M mutations that directly prevent the binding of H3K36me2/3 writer NSD1/2, thus reducing PRC2-H3K36me2 interaction and increasing H3K27me3 levels." (PMID 36589746, 2022). "The interaction between SMARCB1 and NSD1 is essential for the deposition of H3K36me2 in the genome, which is a marker for better prognosis in sarcoma." (PMID 36589746, 2022).
Silver-Russell syndrome (2 papers, 2021 to 2022). Silver-Russell syndrome is characterized by growth retardation with antenatal onset, characteristic facies and limb asymmetry. "NSD1 5q35 duplication has been also detected in patients with Silver-Russell syndrome (SRS) features, which is a growth retardation disorder characterized by facial dysmorphia and body asymmetry." (PMID 36230787, 2022).
squamous cell carcinoma (2 papers, 2017 to 2024). A carcinoma arising from squamous epithelial cells. "This is apparent in NSD1-inactivated squamous cell carcinoma subtypes, where concurrent hypomethylation and overexpression of developmental transcription factors such as PIWIL243, ELF532, TBX633, and FOXH134 occurs." (PMID 29213088, 2017). "Utilizing the same validated shRNA targeting NSD1, we achieved effective knockdown, as confirmed by Western blot analysis using three histologically different cell lines for RPPA validation: JHU 011, laryngeal, Cal27, tongue and FaDu, hypopharyngeal squamous cell carcinoma cell lines." (PMID 38539515, 2024).
viral infection (2 papers, 2018 to 2020). "For example, in Bombyx mori lepidoptera, resistance to Bombyx mori densovirus type 1 or 2 (BmDV1 & BmDV2) is controlled by recessive non-susceptibility genes, nsd-1 and -248,49, which affect distinct stages of the viral infection pathway." (PMID 33122748, 2020). "Nid-1 was shown to be required for a virus infection step that occurs after NSD-1 functions." (PMID 29743532, 2018).
acute erythroleukemia (1 paper, 2020). "Nsd1 gene inactivation during late stage fetal liver hematopoiesis induced a fully penetrant lethal disease that phenocopied several aspects of acute erythroleukemia, a rare form of human AML6." (PMID 32533074, 2020). "Targeted Nsd1 gene inactivation during late fetal hematopoiesis in mice leads to malignant accumulation of erythroblasts phenocopying human acute erythroleukemia." (PMID 32533074, 2020).
adenoma (1 paper, 2013). A neoplasm arising from the epithelium. "Quantitative analysis of microarray data confirmed that these methyltransferases, which included Setd3, Setd5, Suv39h2, Smyd3, Prmt3, Prmt6, Nsd1, and Nsd2 were up-regulated in metastases compared to adenomas, carcinomas, or disseminated cells." (PMID 23520493, 2013).
adrenocortical tumors (1 paper, 2014). "Additionally, the amplification of the IGFBP3, FGFR4 (data not shown), and NSD1 (data not shown) genes was also detected in this carcinoma, but IGF1R amplification was not demonstrated in the remaining cases with adrenocortical tumors." (PMID 25110710, 2014).
brain tumors (1 paper, 2022). "Set2 homologs, including NSD1, NSD2, NSD3, and SETD2, are frequently mutated, translocated, or amplified in a variety of human cancers, and oncohistone mutations that dysregulate H3K36 methylation cause pediatric brain tumors." (PMID 35263330, 2022).
cerebrovascular diseases (1 paper, 2021). "We describe two patients with NSD1 deletion, who presented with early-onset, or recurrent cerebrovascular diseases (CVDs)." (PMID 34031356, 2021).
COVID-19 (1 paper, 2021). A disease caused by infection with severe acute respiratory syndrome coronavirus 2. "The mono-CD16+ cell population in COVID-19 patients showed reduced transcription levels of genes related to lysine degradation (NSD1, KMT2E, and SETD2) and elevated transcription levels of genes involved in OXPHOS (ATP6V1B2, ATP5A1, ATP5E, and ATP5B), which may inhibit M2-like polarization." (PMID 33936072, 2021). "In mono-CD16+ cells in COVID-19 patients, we found reduced lysine degradation (downregulation of NSD1, KMT2E, and SETD2) and enhanced OXPHOS, which may inhibit M2 macrophage polarization and differentiation through the cAMP and MAPK signaling pathways or the PI3K, AKT and mTOR signaling pathways." (PMID 33936072, 2021). "In module 1, NSD1, KMT2E, and SETD2, which are histone lysine methyltransferases involved in cell development and differentiation, were expressed at lower levels in COVID-19 patients." (PMID 33936072, 2021).
diffuse intrinsic pontine glioma (1 paper, 2025). A neuroglial tumor that arises from the middle portion of the brain stem. "Furthermore, the unbalanced activation of NSD1 and expansion of H3K36me2 domains are suggested to mediate the oncogenic effect of the so-called oncohistone mutant, H3K27M, in diffuse intrinsic pontine glioma." (PMID 40118455, 2025).
growth (1 paper, 2012). The increase in size or mass of an entire organism, a part of an organism or a cell. "However dermal fibroblasts do express NSD1 and dermal fibroblasts have successfully been used to elucidate molecular mechanisms underlying growth disorders." (PMID 23155469, 2012).
hypopharyngeal tumor (1 paper, 2017). "In this study, we performed whole-exome sequencing (WES) of 23 hypopharyngeal tumor and paired adjacent normal tissue and confirmed the expression of NSD1 and PRB4 in an independent cohort containing 88 hypopharyngeal tumor and 36 adjacent normal tissues." (PMID 29156722, 2017).
hypospadias (1 paper, 2022). Hypospadias is the displacement of the urethral meatus on the ventrum of the penis. "SRO018 is within this locus and is composed of only cases with duplications; this SRO contains candidate genes DBN1 and NSD1, which may contribute to hypospadias etiology in these cases." (PMID 35457073, 2022).
Inguinal hernia (1 paper, 2022). Protrusion of the contents of the abdominal cavity through the inguinal canal. "The grid visualization also highlights the presence of phenotypes in the proband that has predominantly or only been observed in NSD1 probands (e.g., absent/small foot bones) or in SMARCC2 probands (e.g., thick eyebrows, inguinal hernia)." (PMID 36303224, 2022).
kidney cancer (1 paper, 2019). Primary or metastatic malignant neoplasm involving the kidney. "In contrast, mRNA levels of WHSC1L1, ASH1L, and NSD1 were more than onefold lower in kidney cancer cell lines." (PMID 30755832, 2019).
laryngeal squamous cell carcinoma (1 paper, 2023). A squamous cell carcinoma that arises from the larynx. "Recent studies reported truncating NSD1 mutations in laryngeal squamous cell carcinoma, which were accompanied with a better prognosis and global DNA hypomethylation." (PMID 37240283, 2023).
liver disease (1 paper, 2019). "In the context of HCC however, the regulatory mechanism of NSD1 remains largely unknown, with only a handful of studies showing a possible connection between NSD1 and liver disease." (PMID 31727171, 2019).
male infertility (1 paper, 2019). The inability of the male to effect fertilization of an ovum after a specified period of unprotected intercourse. "Like NSD1, it has not been described in relation to TGCT, but it seems to be involved in spermatogenesis and its aberrations may be related to male infertility." (PMID 31500094, 2019).
mood disorder (1 paper, 2020). A cognitive disorder a disturbance in which the person's mood is hypothesized to be the main underlying feature. "Our patient with PNES and an NSD1 mutation had normal neurodevelopment, an onset of PNES at 12 years of age, a history of mood disorder, and no history of febrile seizures or family history of seizures." (PMID 32938993, 2020).
Myelodysplasia (1 paper, 2021). Clonal hematopoietic stem cell disorders characterized by dysplasia (ineffective production) in one or more hematopoietic cell lineages, leading to anemia and cytopenia. "When fused to the N-terminus of NUP98, the NSD1-SET gains transforming activities in hematopoietic cells, resulting in myelodysplasia and AML, and the presence of a NUP98-NSD1 (and other NUP98-fusions) is often associated with primary resistance to chemotherapy." (PMID 34575025, 2021).
myeloid leukemia (1 paper, 2024). A clonal proliferation of myeloid cells and their precursors in the bone marrow, peripheral blood, and spleen. "Mutations in ATM, MGA, KMT2A, MLLT10, NSD1, and TET2 have been commonly identified in several hematological neoplasms, including both acute lymphoid and myeloid leukemia." (PMID 38672648, 2024).
oral cavity tumors (1 paper, 2023). "NSD1 mutations were preferentially laryngeal, while almost all CASP8 mutations were in oral cavity tumors." (PMID 37081260, 2023).
pancreatic ductal adenocarcinoma (1 paper, 2022). An infiltrating adenocarcinoma that arises from the epithelial cells of the pancreas. "In pancreatic ductal adenocarcinoma, a high level of NSD1 is significantly correlated with the advanced clinical stage." (PMID 35888078, 2022).
rhabdoid tumor (1 paper, 2024). An aggressive malignant embryonal neoplasm usually occurring during childhood. "On a brighter note, inhibition of the H3K36 demethylase KDM2A was recently demonstrated to rescue resistance to EZH2 inhibition conferred by loss of the H3K36 methyltransferase NSD1 in SMARCB1-deficient rhabdoid tumor cell lines." (PMID 39403928, 2024).
rhabdomyosarcoma (1 paper, 2024). A rare aggressive malignant mesenchymal neoplasm arising from skeletal muscle.
Skin cutaneous melanoma (1 paper, 2022). "Cutaneous melanoma has a very high prevalence of NSD1 somatic mutations comparable to other cancer types that were discussed previously in this review." (PMID 36230787, 2022). "Skin cutaneous melanoma (SKCM TCGA dataset) showed NSD1 alterations in 12% of the cases (n = 43/363)." (PMID 36230787, 2022).
Sos (1 paper, 2023). "Molecular analysis of the NSD1 gene (nuclear receptor binding SET domain containing protein 1) reduces diagnostic uncertainty in patients with suspected SoS and allows for diagnosis to be confirmed." (PMID 36833222, 2023). "Our results, in agreement with other European studies, confirm that the intragenic point mutations of the NSD1 gene are the main cause of SoS in Western patients and that the condition appears as a haploinsufficiency syndrome." (PMID 36833222, 2023). "SoS usually arises from NSD1 de novo mutations in the affected subject, as also confirmed by 26.9% (32/119) of the cases in the present study." (PMID 36833222, 2023). "Considering all the 1530 total patients with suspected Sos or overgrowth, we identified 13 subjects with 5q35 de novo microdeletions encompassing the entire NSD1 gene." (PMID 36833222, 2023). "Recently, we described two novel short NSD1 isoforms that are expressed in both healthy individuals and in SoS patients." (PMID 36833222, 2023). "The molecular analysis allowed for the identification of 292 patients (281 with clinical suspicion of SoS and 11 with not-specific-overgrowth) with one NSD1 variant out of 1530 patients analyzed, with a detection rate of 19.1% (N = 292/1530)." (PMID 36833222, 2023). "In particular, microdeletions involving the NSD1 gene are very frequent in Japanese patients with SoS, and this finding is not frequently observed in non-Japanese populations, where intragenic point mutations are highly prevalent." (PMID 36833222, 2023).
supraglottic cancers (1 paper, 2020). "NSD1, which is more frequently altered in the supraglottic cancers, is known to have higher mutation rates in HPV-negative patients with a heavy smoking history." (PMID 33396315, 2020).
supraglottic tumors (1 paper, 2020). "We followed up these findings by investigating the impact of NSD1 and DNAH5 on survival within the HPV-negative cohort of glottic and supraglottic tumors." (PMID 33396315, 2020).
syringomyelia (1 paper, 2021). Syringomyelia is characterized by cerebrospinal fluid (CSF)-filled cavities (syrinx) inside the spinal cord, either as a result of a known cause (secondary syringomyelia, SS) or, more rarely, due to an unknown cause (primary syringomyelia, PS). "Our cases 1 and 2, the first with a de novo 5q deletion of about 2 Mb including NSD1, and the second with a de novo rare missense variant in the same gene, showed C1M, accompanied in case 1 by syringomyelia." (PMID 33337535, 2021).
T-cell non-Hodgkin lymphoma (1 paper, 2017). A non-Hodgkin lymphoma of T-cell lineage. "The remaining child had an NSD1 microdeletion and T cell non-hodgkins lymphoma." (PMID 28475857, 2017).
testicular germ cell tumor (1 paper, 2021). A germ cell tumor arising from the testis. "Highly prevalent NSD1 mutations were also found in testicular germ cell tumors, and low NSD1 expression was associated with resistance to cisplatin." (PMID 34575025, 2021).
Turner syndrome (1 paper, 2022). Turner syndrome is a chromosomal disorder associated with the complete or partial absence of an X chromosome. "The pathogenic variants reported comprised one case of mosaic Turner syndrome (45,X) not detected on CMA, and four variants in the genes ARMC4, ANKRD11, GATA4 and NSD1, all of which would have been amenable to detection by whole exome sequencing in the PAGE and CUIMC studies." (PMID 34411415, 2022).
cancer (91 papers, 2012 to 2026). A tumor composed of atypical neoplastic, often pleomorphic cells that invade other tissues. "This inhibition can promote oncogenesis, as evidenced by the frequent occurrence of NSD1 mutations in cancer." (PMID 39336709, 2024). "We show that Y1971 and R2017 are critical residues in NSD1 and their mutation leads to a loss of enzyme activity suggesting that NSD1 acts as a tumor suppressor gene in these cancers." (PMID 37150325, 2023). "The inhibitory loop (INHLOOP) is an amino acid sequence found between SET and Post-SET, normally inhibiting NSD1 function and is associated with abnormal expression of genes in cancer." (PMID 36550402, 2022). "The abnormal expression of NSD1 in different cancers has also been detected, which is associated with tumorigenesis, survival and chemoresistance." (PMID 35888078, 2022). "As an H3K36 di-methyltransferase, NSD1, which was lost in 22 out of 116 cases, is implicated as a tumor suppressor gene mutated frequently in a variety of carcinomas, and associated with global DNA hypomethylation." (PMID 36418292, 2022). "Some studies have suggested an increased risk for SOTOS patients to develop cancer, raising the question about the role of NSD1 mutations in this context." (PMID 34575025, 2021). "Analysis of cancer-associated aberrant CpG promoter methylation revealed epigenetic silencing of NSD1 in human brain tumor cell lines associated with reduced H3K36 methylation." (PMID 34575025, 2021). "Predicted loss-of-function mutations or epigenetic silencing of NSD1 have been described in a variety of human cancers." (PMID 34575025, 2021). "On the disease connections, we used a NSD2 gain-of-function model which led to the discovery of potential therapeutic implication of DNA inhibitors in the related cancers, while the other study only used NSD1 and DNMT3A loss-of-function models." (PMID 31814083, 2020). "The most likely explanation for that is a partial NSD1 depletion in isogenic cells in our experiments versus 100% NSD1 enzymatic inactivation due to mutation in cells derived from different origins of cancer." (PMID 31321084, 2019). "Applied to ~10,000 tumor exomes the approach identifies known and putative CPGs – including the chromatin modifier NSD1 – that contribute to cancer through a combination of rare germline variants and somatic loss-of-heterozygosity (LOH)." (PMID 29973584, 2018). "Genome sequencing has previously established NSD1 as a somatically mutated cancer driver in HNSC21 and LUSC22, and recurrently silenced by methylation in renal cell carcinoma." (PMID 29973584, 2018). "This suggests that RDGVs in NSD1 are causally implicated in ~0.72% of cancers, a similar magnitude of effect as we observe for the well-known cancer predisposition genes BRCA1 (0.64%) and ATM (0.68%)." (PMID 29973584, 2018). "We investigated the possibility that NSD1 mutations affect DNA methylation in other cancers, focusing on cancers for which there were at least ten patients with NSD1 mutations and accompanying DNA methylation data within TCGA data." (PMID 29213088, 2017). "There was significant overlap; 8/14 genes involved in OGID were somatically mutated in a diverse range of cancers (NSD1, EZH2, DNMT3A, PTEN, CHD8, HIST1H1E, MTOR, PIK3CA; p = 1.7 × 10−14)." (PMID 28475857, 2017). "NSD1 inactivation therefore causes epigenetic deregulation across cancer sites, and has implications for immunotherapy." (PMID 29213088, 2017). "LUSC was the only of these cancers in which NSD1 mutations were significantly associated with DNA hypomethylation (p = 0.001)." (PMID 29213088, 2017). "NSD1 is best known as the causative gene for the congenital overgrowth disorder Sotos syndrome, which is associated with mildly increased cancer incidence." (PMID 29213088, 2017).